MUC5AC (mucin 5AC, oligomeric mucus/gel-forming)
Diseases named in the same sentence as MUC5AC in open-access papers (continued):
Sharing a sentence is not in itself a finding about the gene and the disease.
cholangiocarcinoma (17 papers, 2009 to 2024). A carcinoma that arises from the intrahepatic biliary tree (intrahepatic cholangiocarcinoma) or from the junction, or adjacent to the junction, of the right and left hepatic ducts (hilar cholangiocarcinoma). "MUC5AC is tightly connected with the happening of cancers, especially hepatocellular carcinoma and cholangiocarcinoma." (PMID 35294478, 2022). "Most other cancer types with glandular differentiation, such as endometrium cancer, adenocarcinoma of the cervix uteri, adenocarcinoma of the lung and cholangiocarcinoma were also MUC5AC positive in a fraction of cases." (PMID 34547930, 2021). "The presence of mucin MUC5AC in plasma has been reported for one epithelial cancer, cholangiocarcinoma." (PMID 26075384, 2015). "Carbohydrate antigen 19-9 (CA19-9), leucine-rich α2-glycoprotein (LRG1), interleukin 6 (IL6), pyruvate kinase M2 (PKM2), cytokeratin 19 fragment (CYFRA21.1) and mucin 5AC (MUC5AC) have reported utility for differentiating cholangiocarcinoma (CCA) from benign biliary disease." (PMID 29707118, 2018). "Studies have shown that MUC5AC apomucin originating from cholangiocarcinoma (CCA) tissues was detected in patient serum with high sensitivity and specificity." (PMID 39767713, 2024). "MUC1 showed high expression in cholangiocarcinomas and cholangiocellular differentiated areas of cHCC-CCC, whereas MUC2, MUC3, MUC5/6, MUC5AC, MUC6, and MUC7 showed limited usefulness for further differentiation." (PMID 36672443, 2023). "Other tumor markers that have been studied for diagnosis of cholangiocarcinoma include transthyretin (TTR), interleukin-6 (IL-6), mucin-5AC (MUC5AC) and matrix metalloproteinase-7 (MMP-7)." (PMID 25355800, 2015). "Aberrant expression of MUC3, MUC4, MUC5AC and MUC6 has been described in pancreatic intraepithelial neoplasia, and we recently reported that MUC16 is a candidate as a poor prognostic factor in cholangiocarcinoma." (PMID 24722639, 2014). "MUC5AC, which is a gastric-type mucin was not expressed in mass-forming cholangiocarcinoma." (PMID 27933122, 2009).
pancreatic ductal adenocarcinoma (17 papers, 2010 to 2025). An infiltrating adenocarcinoma that arises from the epithelial cells of the pancreas. "We investigated the association between serum MUC5AC (sMUC5AC) levels and patient outcomes in individuals who underwent resection for pancreatic ductal adenocarcinoma (PDA), including those treated with neoadjuvant therapy (NAT) and those who had upfront surgery (UpS) followed by adjuvant therapy." (PMID 40260290, 2025). "Mucin 5AC (MUC5AC) glycoprotein plays a crucial role in carcinogenesis and drug sensitivity in pancreatic ductal adenocarcinoma (PDAC), both individually and in combination with other mucins." (PMID 37175794, 2023). "In a separate study, we found that MUC5AC was significantly associated with TNM stage of pancreatic ductal adenocarcinoma and its vascular invasion than those negative for MUC5AC expression (unpublished data)." (PMID 22027009, 2011). "MUC5AC was found to express in more than 80% of pancreatic ductal carcinoma specimens." (PMID 20492722, 2010). "As Background, we tested MUC5AC expression in 100 specimens of pancreatic ductal carcinoma." (PMID 20492722, 2010). "Proposed cancer progression roles for MUC5AC in adenocarcinoma include overexpression of MUC5AC in intercellular junctions that interfere with the membrane localization of E-cadherin, compromise cell-cell adhesion, and increase migration and invasion of pancreatic ductal adenocarcinoma cells." (PMID 28430953, 2016). "If the diagnosis of pancreatic ductal adenocarcinoma is considered, ductal differentiation can be demonstrated by using additional immunohistochemical markers such as mucin-related glycoproteins (MUC1, MUC5AC) and/or oncoproteins (CEA, B72.3, CA125)." (PMID 33432559, 2021). "Pancreatic ductal adenocarcinoma (PDAC) displays a typical mucin expression pattern which is characterized by MUC1 positive, MUC2 negative, and MUC5AC positive." (PMID 35910854, 2022).
nasal polyps (16 papers, 2014 to 2025). "Studies on the regulation of mucin genes in response to cytokines reported that IL-4, IL-13, IL-8 IL-33, and TNF increase the mRNA and protein expression levels of MUC5AC in nasal polyp-derived epithelial cells." (PMID 33477617, 2021). "Studies on the expression of mucin in nasal polyps by using probes to be directed against unique sequence of mucin molecule (discontinuous repeat probes) show that expression level of MUC5AC is four times higher than MUC2 and is twelve times higher than MUC1." (PMID 32812123, 2020). "When divided the nasal polyps into IL-17Ahigh and IL-17low subgroup, we found the mRNA levels of IL-17A, MUC5AC and act1 were significantly higher in IL-17Ahigh polyp tissues than those in IL-17Alow polyp tissues (p<0.05)." (PMID 24892823, 2014). "Because IL-17A has been proposed to be significantly upregulated in nasal polyps, we firstly examined the expression of IL-17A and MUC5AC, as well as goblet cell hyperplasia, in polyp tissues and normal controls." (PMID 24892823, 2014). "Some studies investigated the pattern of expression of mucin in healthy nasal tissues and nasal polyps, which found that overexpressions of MUC1, MUC4, MUC5AC, and MUC5B are in nasal polyps than in healthy nasal tissues." (PMID 32812123, 2020). "Several studies have shown that the major mucins expressed in chronic sinusitis (CS) are MUC2, MUC5AC, and MUC5B and an inverse relationship was found between MUC2 and MUC5AC expression levels and this was strong in the presence of nasal polyps." (PMID 25691903, 2015). "IL‐13, IL‐4Rα, IL‐13Rα1, and MUC5AC were found to be highly expressed in nasal polyp tissue from patients with eosinophilic chronic rhinosinusitis (ECRS), and IL‐13 expression was positively correlated with MUC5AC expression, indicating that IL‐13 can directly regulate mucin hypersecretion." (PMID 38282195, 2024). "Doxycycline could have the potential to reduce nasal polyp volume by decreasing MMP-9 levels and reducing MUC5AC levels." (PMID 33477617, 2021). "Compared with normal nasal mucosa, the expression of MUC3 and MUC6 in nasal polyps is downregulated, the expression of MUC2 and muc8 in nasal polyps is upregulated, the expression of MUC5AC and MUC5B in CRS is upregulated, and the expression of MUC5AC in nasal polyps far exceeded MUC1 and MUC2." (PMID 32812123, 2020). "In conclusion, this study has shown that treatment with the growth factor EGF upregulates the expression of MUC5AC in HNECs from CRSwNP via a pathway, which is likely to involve PI3K-TMEM16A signalling, and provides novel insights into the molecular mechanism of mucus hypersecretion in nasal polyps." (PMID 32514271, 2020). "Immunohistochemical staining showed strong staining of MUC5AC proteins in the mucosa tissues in patients with CRS, irrespective of nasal polyp presence, compared with the control group." (PMID 31379870, 2019). "Concomitantly, immunohistochemical staining showed that MUC5AC proteins were strongly stained in CRS patients, irrespective of nasal polyp presence, compared with the control group." (PMID 31379870, 2019). "MUC5AC expression was significantly up‐regulated in both chronic rhinosinusitis with nasal polyps (CRSwNP; WMD: 0.52; 95% CI: 0.41–0.63) and chronic rhinosinusitis without nasal polyps (CRSsNP; WMD: 0.42; 95% CI: 0.28–0.56) patients compared to controls." (PMID 39482799, 2024).
lung adenocarcinoma (15 papers, 2013 to 2025). A carcinoma that arises from the lung and is characterized by the presence of malignant glandular epithelial cells. "The aberrant overexpression of Muc5ac is also significantly associated with the development of lung adenocarcinoma (LUAD) mediated by a predisposition to Kras mutation." (PMID 38825648, 2024). "Mucin 5ac (MUC5AC) plays a pivotal role in the development of lung adenocarcinoma (LUAD); however, its role in causing brain metastases remains unknown." (PMID 38825648, 2024). "This chemokine not only triggers MUC5AC expression through the ERK1/2-SP1 signaling cascade but also binds to its receptors on lung adenocarcinoma cells, activating the ERK1/2 pathway and enhancing SP1 binding to the MUC5AC gene promoter." (PMID 40655139, 2025). "The pivotal role of the MUC5AC/ANXA2 signaling axis in facilitating brain metastasis from lung adenocarcinoma underscores its significance in cancer progression." (PMID 40655139, 2025). "In lung adenocarcinoma, MUC5AC was found enriched in brain metastases, with cells expressing MUC5AC progressing to brain metastases via annexin A2 as well as interplay with MMPs." (PMID 39767713, 2024). "Another study found increased Mucin 5ac (MUC5AC) levels in lung adenocarcinoma brain metastases tissue and brain-tropic cell lines." (PMID 39408656, 2024). "Being well-established as a cancer-promoting molecule, MUC5AC has overexpressed in several cancers, which indicates a poor prognosis of lung adenocarcinoma patients." (PMID 37324942, 2023). "The simultaneous upregulation of AQP5 and MUC5AC has also been observed in lung adenocarcinoma cell line." (PMID 29112967, 2017). "IHC analysis with an anti-MUC5AC antibody (45M1 clone) was performed on normal (n = 10), primary lung adenocarcinoma (n = 10), primary lung squamous cell carcinoma (n = 29), squamous cell carcinoma brain metastasis (n = 13) and adenocarcinoma brain metastasis (n = 11) tissues." (PMID 38825648, 2024). "In our model, the hypersecretion of MUC5AC by Calu-3 cells, derived from a lung adenocarcinoma, was induced by deprivation of any FBS supplementation only, while no visible over-production of MUC5AC was observed in long-term cell cultures with reduced FBS supplementation." (PMID 33758289, 2021). "In summary, the MUC5AC/ANXA2 signaling pathway, modulated by CCL22, exerts a profound influence on the development of brain metastases from lung adenocarcinoma." (PMID 40655139, 2025).
lung disease (15 papers, 2011 to 2025). "For MUC1 and MUC5AC alleles, which had bimodal distributions, we tested “short” (S) versus “long” (L) alleles for association with CF lung disease severity." (PMID 21998660, 2011). "In contrast, there was robust association between the MUC5AC 6.4 kb allele and severe lung disease, when the 6.4 kb allele was considered as the designated allele (D), versus all other alleles (p = 1.4×10−5)." (PMID 21998660, 2011). "The odds ratio for 1 or 2 copies of the 6.4 kb MUC5AC VNTR allele to be associated with severe CF lung disease is 2.5." (PMID 21998660, 2011). "Whatever is the case, the alleles described here might be relevant for other serious lung diseases, and further studies to define the mechanistic link between the MUC5AC VNTR functional variants and CF lung disease are warranted." (PMID 21998660, 2011). "Association of MUC5AC VNTR allele sizes with lung disease severity (“Severe” versus “Mild”)†." (PMID 21998660, 2011). "Since the 6.4 kb allele of MUC5AC was associated with severe CF lung disease, we next tested whether the severity-associated 6.4 kb allele could be distinguished from other alleles (especially the 6.3 kb allele, which is similar in size and in frequency), based upon LD patterns with nearby SNPs." (PMID 21998660, 2011). "MUC5B and MUC5AC are the most common gel forming mucins in the airways of human CF and CF-like lung disease mouse model." (PMID 40496925, 2025). "Neutrophil elastase also plays a direct role in mucus hyper production and mucin over secretion in lung disorders by directly activating the MUC5AC gene." (PMID 36569308, 2022). "Considering that an increase in mucous‐secreting cells is a common feature of several lung diseases, we also evaluated the production of the two main mucins in the lung: Muc5ac and Muc5b." (PMID 34170075, 2021). "These were MUC1, MUC2, MUC5AC and MUC7 whose encoded proteins are of recognized importance in normal airway defense, and/or prior studies that indicate they play a role in diseases of the lung, and other inflammatory or malignant disease." (PMID 21998660, 2011). "However, when we tested the alternative hypothesis, i.e., that individual VNTR size variants could associate with lung disease, we discovered a robust association between the MUC5AC 6.4 kb VNTR allele and severe lung disease (p = 6.2×10−4 after Bonferroni correction)." (PMID 21998660, 2011). "Using Southern Blot methods that define MUC5AC allele lengths more precisely than previously reported, we identified robust association of a specific MUC5AC VNTR allele (6.4 kb, HinfI-digested DNA) and severe CF lung disease." (PMID 21998660, 2011). "Our data also show a novel link between the MUC5AC 6.4 kb VNTR allele and severity of CF lung disease." (PMID 21998660, 2011). "Given its role in asthmatic lung disease, MUC5AC represents a potential therapeutic target where a gene delivery approach could be leveraged to modulate its expression." (PMID 40849510, 2025). "Our findings strengthen the hypothesis that MUC5AC and MUC5B are yet another contributing factor to smoking-associated lung disease progression." (PMID 39769414, 2024). "Analysis of SNP data from candidate gene studies of MUC1, MUC2, and MUC5AC showed that none of the genotyped SNPs were highly associated with lung disease severity." (PMID 21998660, 2011). "Additionally, a borderline significant association was found in males between MUC5AC and MUC5B, which highly colocalizes with a MUC5B eQTL in lung tissue, and several studies have linked this variant to pulmonary disease like idiopathic pulmonary fibrosis and COVID-1926,27." (PMID 40021682, 2025). "MUC5AC VNTR length variants (which may confer differing structural properties), could alter the function of the airway mucus, affecting the inflammation/defense status and the progression of lung disease." (PMID 21998660, 2011).
lung disease (continued). "In an airway inflammation model stimulated by Asian sand dust, upregulation of mucin (MUC)5AC and MUC5B stimulates mucus secretion; significantly, mucus cross-linking exacerbates pulmonary disease." (PMID 36133804, 2022). "Increased EGFR signaling, TGF-α production, and mucins (MUC5AC and MUC5B) expression have been reported in the airways of CF patients; however, the causative role of EGFR in CF-like lung disease has not been demonstrated, thus warranting further investigation." (PMID 40406132, 2025). "Collectively, these results suggest that MUC5AC and MUC5B might be involved in COPD pathogenesis or may be biomarkers of lung disease." (PMID 39769414, 2024). "Mucus taken from the endotracheal tubes (ETT) of patients with no lung disease actually produced proportions of mucin similar to those found in the sputum of patients experiencing CF exacerbations (12% more MUC5AC in CF exacerbation vs. ETT, 4% less MUC5B in CF exacerbation vs. ETT)." (PMID 38674677, 2024).
viral infection (15 papers, 2013 to 2024). "Exogenous MUC5AC also enhanced RV-induced neutrophil elastase concentrations, suppressed SLPI production, and increased pulmonary bacterial loads, further suggesting a possible role for MUC5AC in inhibiting antibacterial responses during viral infection." (PMID 35239513, 2022). "We additionally observed that exogenous MUC5AC protein administration augmented RV-induced proinflammatory responses in mice, which also suggests that MUC5AC is related to enhanced airway inflammation during viral infection." (PMID 35239513, 2022). "The lower basal concentration and reactivity of MUC5AC to viral infection made MUC5AC a more sensitive biomarker of airway inflammatory responses to viral infection." (PMID 35239513, 2022). "The protective role of mucins during IAV infection was demonstrated by overexpression of the soluble mucin Muc5ac in mice, which protected against viral infection." (PMID 33184103, 2020). "Viral infection, which is known as the primary cause of COPD exacerbations, induces mucus secretion and the production of a major secreted mucin, MUC5AC." (PMID 27677339, 2016). "On day 4, after virus infection lung tissue MUC5AC mRNA levels were increased in elastase + RV- compared with PBS + RV- and elastase + UV-treated mice." (PMID 25783022, 2015). "Our data indicate OPN-deficiency led to enhanced mucus secretion and reduced viral loads in the lung; this resembles the phenomena observed when IL-13 and MUC5AC are overexpressed in mice and the animals are protected from viral infection." (PMID 24558422, 2014). "Our data identified a proinflammatory role for MUC5AC during viral infection and suggest that MUC5AC inhibition may ameliorate COPD exacerbations." (PMID 35239513, 2022). "This increase may be due to mice swallowing the excess mucus produced in the airways after infection or it may be that Muc5ac expression in colonic goblet cells is stimulated by the viral infection." (PMID 29483910, 2018). "In our previous study, we confirmed that TLR3 was expressed in NCI-H292 cells, a human pulmonary mucoepidermoid carcinoma cell line, and a synthetic dsRNA analogue, poly(I:C), used as a TLR3 ligand to mimic viral infection, induced the expression and release of MUC5AC from the cells." (PMID 27677339, 2016). "We demonstrated that dsRNA and viral infection induce the release of ATP via pannexin channel and that extracellular ATP is involved in the expression and release of MUC5AC via P2R, especially P2Y2R, in NCI-H292 cells and differentiated HBECs from COPD patients." (PMID 27677339, 2016). "However, whether the increase in mucin is due to viral infection stimulating Muc5ac expression in colonic goblet cells remains to be investigated." (PMID 37577440, 2023). "Also, MUC5AC secretion was shown to increase upon virus infection." (PMID 35558099, 2022). "Airway mucins MUC5AC and MUC5B are the predominant gel-forming mucins in COPD, and CS exposure and frequent bacterial or viral infection synergistically amplify MUC5AC levels." (PMID 35774797, 2022). "In conclusion, MUC5AC and MUC5B were both induced during viral infections in COPD." (PMID 35239513, 2022). "ATP is involved in the expression and release of a major airway mucin, MUC5AC, mainly via P2Y2R and it was suggested that modulation of this pathway could be useful clinically for mucus hypersecretion following viral infections." (PMID 28993732, 2017). "Recently, we and others have shown that viral infection and the stimulation of TLR3 induces the expression and production of MUC5AC in airway epithelial cells mainly via epidermal growth factor receptor (EGFR) and extracellular signal-regulated kinase (ERK) signaling pathways." (PMID 27677339, 2016).